PLA2G3 (phospholipase A2 group III)
Description:
Secretory calcium-dependent phospholipase A2 that primarily targets extracellular phospholipids. Hydrolyzes the ester bond of the fatty acyl group attached at sn-2 position of phospholipids without apparent head group selectivity. Contributes to phospholipid remodeling of low-density lipoprotein (LDL) and high-density lipoprotein (HDL) particles. Hydrolyzes LDL phospholipids releasing unsaturated fatty acids that regulate macrophage differentiation toward foam cells. May act in an autocrine and paracrine manner. Secreted by immature mast cells, acts on nearby fibroblasts upstream to PTDGS to synthesize prostaglandin D2 (PGD2), which in turn promotes mast cell maturation and degranulation via PTGDR. Secreted by epididymal epithelium, acts on immature sperm cells within the duct, modulating the degree of unsaturation of the fatty acyl components of phosphatidylcholines required for acrosome assembly and sperm cell motility. Facilitates the replacement of fatty acyl chains in phosphatidylcholines in sperm membranes from omega-6 and omega-9 to omega-3 polyunsaturated fatty acids (PUFAs). Coupled to lipoxygenase pathway, may process omega-6 PUFAs to generate oxygenated lipid mediators in the male reproductive tract (By similarity). At pericentrosomal preciliary compartment, negatively regulates ciliogenesis likely by regulating endocytotic recycling of ciliary membrane protein. Coupled to cyclooxygenase pathway provides arachidonate to generate prostaglandin E2 (PGE2), a potent immunomodulatory lipid in inflammation and tumorigenesis. At colonic epithelial barrier, preferentially hydrolyzes phospholipids having arachidonate and docosahexaenoate at sn-2 position, contributing to the generation of oxygenated metabolites involved in colonic stem cell homeostasis. Releases C16:0 and C18:0 lysophosphatidylcholine subclasses from neuron plasma membranes and promotes neurite outgrowth and neuron survival.
Synonyms: sPLA2-III; GIII-SPLA2; SPLA2III
Tractability: Small molecule: a high-quality ligand is known. Antibody: UniProt places it where antibodies can reach, with high confidence; its Gene Ontology location is reachable by antibodies, with high confidence; UniProt predicts a signal peptide or a membrane-spanning region. PROTAC: a small molecule that binds it is known.
Target class: Enzyme; Hydrolase
Gene: Protein-coding gene on chromosome 22 (31,134,765 to 31,140,508, reverse strand). Ensembl gene ENSG00000100078.
Subcellular location: Secreted; Cell membrane; Cytoplasm, cytoskeleton, microtubule organizing center, centrosome, centriole; Recycling endosome
Subcellular location (Human Protein Atlas): Endoplasmic reticulum; Golgi apparatus; Predicted to be secreted
Pathways (Reactome):
Metabolism: Acyl chain remodelling of PC; Acyl chain remodelling of PE; Acyl chain remodelling of PG
Gene Ontology:
Molecular function: phospholipase A2 activity; phospholipase activity
Biological process: cilium assembly; high-density lipoprotein particle remodeling; low-density lipoprotein particle remodeling; negative regulation of gene expression; negative regulation of neuron apoptotic process; phosphatidic acid metabolic process; phosphatidylcholine metabolic process; phosphatidylethanolamine metabolic process; phosphatidylglycerol metabolic process; phosphatidylinositol metabolic process; phosphatidylserine metabolic process; positive regulation of histamine secretion by mast cell; positive regulation of macrophage derived foam cell differentiation; positive regulation of neuron projection development; positive regulation of prostaglandin biosynthetic process; regulation of endocytic recycling; phospholipid metabolic process; arachidonate secretion; positive regulation of cell differentiation; positive regulation of mast cell differentiation
Cellular component: centriole; extracellular region; plasma membrane; recycling endosome
Genetic constraint (gnomAD): Loss-of-function variants: 40 observed, 53.84 expected, observed/expected ratio (o/e) 0.74, 90% interval 0.58 to 0.97. The upper end of that interval is the gene's LOEUF score, 0.97, which puts it in group 4 of 6, group 1 being the genes least tolerant of losing a copy. Missense variants: 677 observed, 673.69 expected, observed/expected ratio (o/e) 1, 90% interval 0.94 to 1.07. Synonymous variants: 293 observed, 269.45 expected, observed/expected ratio (o/e) 1.09, 90% interval 0.99 to 1.2.
Homologues: Orthologues: chimpanzee PLA2G3 (98% identical), macaque PLA2G3 (93% identical), dog PLA2G3 (75% identical), pig PLA2G3 (74% identical), rabbit PLA2G3 (70% identical), guinea pig PLA2G3 (70% identical), rat Pla2g3 (66% identical), mouse Pla2g3 (66% identical), zebrafish pla2g3 (23% identical), tropical clawed frog pla2g3 (23% identical), Drosophila melanogaster GIIIspla2 (14% identical), Drosophila melanogaster CG30503 (10% identical), and 1 more. Paralogues in human: PROCA1 (11% identical).
Diseases named in the same sentence as PLA2G3 in open-access papers:
PLA2G3 is named in the same sentence as 49 diseases in open-access papers, as found by Europe PMC text mining. Sharing a sentence is not in itself a finding about the gene and the disease. The quoted sentences say what the papers report.
colorectal cancer (5 papers, 2008 to 2025). A primary or metastatic malignant neoplasm that affects the colon or rectum. "To further assess the relationship between the ameliorating effect of sPLA2-III deficiency on colitis and that on colorectal cancer, we next subjected Pla2g3−/− and control Pla2g3+/+ mice to chronic DSS treatment." (PMID 28947740, 2017). "PLA2G3 was upregulated in ovarian cancer, melanoma, and colorectal cancer and improved the poor prognosis and malignant progression of cancer." (PMID 36246400, 2022). "Our present study employing Pla2g3−/− mice provides compelling evidence for the exacerbating role of sPLA2-III in colorectal cancer." (PMID 28947740, 2017).
ovarian carcinoma (4 papers, 2014 to 2023). A malignant neoplasm originating from the surface ovarian epithelium. "Loss of HSulf-1 induced an increase in PLA2G3 expression that may lead to the accumulation of LD in ovarian cancer." (PMID 25225614, 2014). "Though recent studies reveal that high PLA2G3 expression significantly correlates with poor prognosis in several cancers, however, role of PLA2G3 in ovarian cancer (OC) pathogenesis is still undetermined." (PMID 34082797, 2021). "Our study in ovarian cancer provides significant novel insights into the down regulation of PLA2G3 towards sensitizing the cancer cells to chemotherapy." (PMID 34082797, 2021). "PLA2G3 is a group of enzymes that hydrolyze phospholipids to release fatty acids (FA) and lysophospholipids regulating lipid metabolism of transformed cells, and the downregulation of PLA2G3 inhibits the tumor growth and promotes chemo-sensitization in ovarian cancer." (PMID 38093298, 2023).
Alzheimer disease (3 papers, 2014 to 2022). A progressive, neurodegenerative disease characterized by loss of function and death of nerve cells in several areas of the brain leading to loss of cognitive function such as memory and language. "Importantly PLA2G3 drives apoptotic cell death and its overexpression has been associated with Alzheimer's disease." (PMID 25202975, 2014). "Some findings show that a key role of PLA2G3 is that it is involved in the initiation and/or progression of Alzheimer’s disease, which provokes apoptotic cell death." (PMID 35743951, 2022). "Among those genes with significantly changed expression by array analysis, Pla2g3 is the only one that has been reported to be involved in Alzheimer’s disease and we first focused on this gene." (PMID 26637123, 2015).
colon cancer (3 papers, 2008 to 2020). "Furthermore, Pla2g3−/− mice are less susceptible to dextran sulfate-induced colitis, implying that the amelioration of colonic inflammation by sPLA2-III ablation may underlie the protective effect against colon cancer." (PMID 28947740, 2017). "Unlike the situation in human colorectal cancer, however, colorectal Pla2g3 expression was decreased in this colon cancer model, probably reflecting tumor heterogeneity or species difference." (PMID 28947740, 2017). "As expected, the expression levels of many lipid-metabolic genes were altered in AOM-treated Pla2g3−/− mice compared with Pla2g3+/+ mice, likely as a result of the marked attenuation of colon cancer in the null mice." (PMID 28947740, 2017). "In left-sided adenocarcinomas, a first cluster (cluster I) of upregulated genes was observed containing PLA2G3 and several genes related to colon cancer such as HD-6, MMP-7 and Il-8." (PMID 18212756, 2008). "Importantly, Pla2g3−/− mice are resistant to several models of colon cancer." (PMID 33086624, 2020). "Given that all sporadic colon cancers exhibit some aspects of inflammation and that the pathogenesis of some types of colon cancer is associated with IBD1, we hypothesized that the protection against colon cancer in Pla2g3−/− mice might be based on an ameliorated inflammatory response." (PMID 28947740, 2017).
colitis (2 papers, 2017 to 2020). Inflammation of the colon. "On day 9, necropsy revealed drastic shortening of the colon length in Pla2g3+/+ mice, whereas Pla2g3−/− mice were protected from this severe sign of colitis." (PMID 28947740, 2017).
contact dermatitis (2 papers, 2021 to 2022). An inflammatory skin condition caused by direct contact between the skin and either an irritating substance or an allergen. "Furthermore, mast cell-specific Pla2g3-deficient mice, as well as mast cell-deficient KitW-sh mice reconstituted with mast cells prepared from global Pla2g3–/– mice, display a significant reduction of irritant contact dermatitis (ICD) and an aggravation of Th1-dependent CHS." (PMID 35833146, 2022). "Furthermore, MC-specific Pla2g3-deficient mice, as well as MC-deficient KitW-sh mice reconstituted with MCs prepared from global Pla2g3-null mice, displayed a significant reduction in irritant contact dermatitis (ICD) and an aggravation of contact hypersensitivity (CHS)." (PMID 34359862, 2021).
lung adenocarcinoma (2 papers, 2023 to 2024). A carcinoma that arises from the lung and is characterized by the presence of malignant glandular epithelial cells. "The low expression levels of down-regulated DEGs PLA2G3, PCP4L1, NINJ2, MIR186, and KLRG1 were also statistically correlated with a shorter OS in lung adenocarcinoma." (PMID 38183079, 2024).
male infertility (2 papers, 2020 to 2024). The inability of the male to effect fertilization of an ovum after a specified period of unprotected intercourse. "Damage in the integrity of microtubule doublet structure has been shown to be associated with sperm motility defects and male infertility, as seen for the deletion of Ccdc176, Tmem232, Cfap97d1, Dnah17, Trll9, Pla2g3 and Vdac3 in mice." (PMID 38750428, 2024). "Similarly, deletion of Vdac3, Pla2g3, and DNAH17 caused instability of sperm microtubule doublets 4–7, associated with sperm motility defects and male infertility." (PMID 32785227, 2020).
anaphylaxis (1 paper, 2021). An acute hypersensitivity reaction that occurs from exposure to an allergen. "Collectively, these results indicate that the ablation of Pla2g3 specifically in MCs leads to impaired MC maturation, accompanied by reduced MC-associated anaphylaxis and irritant dermatitis, in vivo." (PMID 34359862, 2021).
asthenozoospermia (1 paper, 2024). "For example, Dnah17, Vdac3, and Pla2g3 loss induces destabilization of sperm MTDs 4–7, causing asthenozoospermia, whereas Ccdc176 KO mouse sperm exhibit axonemal structure deficiency in the absence of Dmt1 and/or 9 (missing Dmt1, Dmt9, or both)." (PMID 39516485, 2024).
atherosclerosis (1 paper, 2015). A disease characterized by the build-up of fatty material and calcium deposition in the arterial wall resulting in partial or complete occlusion of the arterial lumen. "Human Pla2g3 has been suggested to be involved in atherosclerosis in apo-E deficient mice, and its overexpression causes spontaneous skin inflammation in human Pla2g3-transgenic mice." (PMID 26637123, 2015).
colon adenocarcinoma (1 paper, 2008). "Interestingly, we observed marked alterations in the expression levels of PLA2G2D, PLA2G5 and PLA2G3 in colon adenocarcinomas." (PMID 18212756, 2008).
gastric cancer (1 paper, 2008). A primary or metastatic malignant neoplasm involving the stomach. "It will be of interest to determine whether the expression of PLA2G3 is related to the activation of the Wnt/β-cat/Tcf-4 pathway, as already suggested for PLA2G2A in gastric cancer." (PMID 18212756, 2008).
lung fibrosis (1 paper, 2023). "Interestingly, all these six dominant isoforms were found to be present only in structural cells like fibroblasts (PLA2G2A and PLA2G5), mesothelial cells (PLA2G2A) and epithelial cells (PLA2G1B, PLA2G3, PLA2G10 and PLA2G12A) that are key players in lung fibrosis." (PMID 37048117, 2023).
meningitis (1 paper, 2022). A disorder characterized by acute inflammation of the meninges of the brain and/or spinal cord. "Subcytolytic concentrations of SLY upregulated the hCMEC release of TNF-α, which led to an increased expression of PLA2G3, destroyed the integrity of the BBB, and may play an important role in the development of S. suis induced meningitis." (PMID 35743951, 2022).
metastatic tumors (1 paper, 2021). "Given our data that PLA2G3-KD inhibits metastasis in vivo, analyzing primary ovarian tumors vs. their autologous metastatic tumors (bowel/omental Mets) in patients, may be more informative to determine the role of PLA2G3 in the OC prognosis." (PMID 34082797, 2021).
oral cancer (1 paper, 2016). "Somatic mutations in arachidonic acid metabolism pathway genes, such as PLA2G3, PTGIS and GGT7, prolong post-treatment disease-free survival of patients with oral cancer." (PMID 27888627, 2016).
polyposis (1 paper, 2017). "Although polyposis in the small intestine was barely affected by sPLA2-III depletion, the number of larger polyps was significantly lower in the colon of Pla2g3−/−ApcMin/+ mice than in that of Pla2g3+/+ApcMin/+ mice." (PMID 28947740, 2017).
schizophrenia (1 paper, 2024). A major psychotic disorder characterized by abnormalities in the perception or expression of reality. "This study indicated that in the discovery stage, an increased copy number of PLA2G6 and the deletion of PLA2G3, PLA2G4A, PLA2G4F and PLA2G12F was associated with increased risk of schizophrenia." (PMID 38816399, 2024).
cancer (6 papers, 2008 to 2023). A tumor composed of atypical neoplastic, often pleomorphic cells that invade other tissues. "cPLA2α (PLA2G4A), iPLA2β (PLA2G6), sPLA2-IIA (PLA2G2A) and sPLA2-III (PLA2G3) are recognized to play a tumorigenic role in cancer." (PMID 38017485, 2023). "We found that both PFK158 inhibitor-mediated and genetic downregulation of PLA2G3 resulted in increased number of percent ciliated cells and inhibited cancer progression." (PMID 34082797, 2021). "Collectively, these results suggest that PLA2G3 KD increased sensitivity of the cancer cells to autophagy-induced cytotoxicity upon treatment with platinum drugs." (PMID 34082797, 2021). "Given that LD-rich cancer cells exhibit chemo-resistive properties, we investigated whether PLA2G3 KD sensitizes cancer cells to cisplatin/carboplatin-induced cytotoxicity." (PMID 34082797, 2021). "The Pla2g3−/− colon displays significant reduction of several lysophospholipids including lysophophatidic acid (LPA) and lysophosphatidylinositol (LPI), which may promote colon inflammation or cancer through their receptors LPA2 and GPR55, respectively." (PMID 33086624, 2020).
tumor (6 papers, 2008 to 2023). "The decreased induction of Ptgs2 (encoding COX-2) and Ptges (encoding PGE2 synthase (mPGES-1)) in Pla2g3−/− mice relative to Pla2g3+/+ mice implies that the tumor-associated production of PGE2, a pro-tumorigenic prostanoid, is reduced by the lack of sPLA2-III." (PMID 28947740, 2017). "PLA2G3-KO tumor-bearing mice showed a significant reduction in tumor growth and metastatic spread compared to the SCG-control group." (PMID 34082797, 2021). "PLA2G3 knockout OVCAR5 xenograft in combination with carboplatin on tumor growth and metastasis was assessed in vivo." (PMID 34082797, 2021). "AOM treatment induced the development of multiple tumors in the middle to distal colon of Pla2g3+/+ mice, whereas tumor development was markedly attenuated in Pla2g3−/− mice." (PMID 28947740, 2017). "Similar data were obtained for samples from the right colon, with a 22-fold increased expression in tumour vs normal mucosa for PLA2G3, and 10- and 44-fold reduced expression for PLA2G2D and PLA2G5, respectively." (PMID 18212756, 2008). "More specifically, we show for the first time that targeting PLA2G3 by PFK158-induced autophagy plays a role in restoration of PC in OC cells and reduces tumor progression." (PMID 34082797, 2021). "While down-regulation of genes such as CYP4A11, PLA2G4A, PLA2G3, LTC4S, CYP27A1, HMGCS2 and PDPK1 reduced patient overall survival time in most tumor types." (PMID 31074374, 2019). "sPLA2-III deletion decreased the total tumor burden in the colon after AOM treatment, the number of large (>2 mm in diameter) and small (<2 mm) tumors being markedly lower in Pla2g3−/− mice than in Pla2g3+/+ mice." (PMID 28947740, 2017).
adenocarcinoma (1 paper, 2008). A common cancer characterized by the presence of malignant glandular cells. "In adenocarcinomas from left and right colon, the expression of PLA2G3 was increased by up to 40-fold, while that of PLA2G2D and PLA2G5 was decreased by up to 23- and 14-fold." (PMID 18212756, 2008). "Interestingly, we observed a 40-fold increase in PLA2G3 expression in the adenocarcinomas." (PMID 18212756, 2008). "We found that the expression pattern of PLA2G3 was more similar to that of MMP-7, which was also increased in both left and right colon adenocarcinomas." (PMID 18212756, 2008).
infection (1 paper, 2022). The state of being infected such as from the introduction of a foreign agent such as serum, vaccine, antigenic substance or organism. "Since PLA2G3 expression did not increase until 3 h post infection (hpi), we speculated that SLY did not affect PLA2G3 expression directly and aimed to further investigate what happens within this 3 h window." (PMID 35743951, 2022).
PLA2G3 also shares sentences with these, for which no sentence is quoted: abscesses (1 paper); adenoma (1); allergic reaction (1); Ascites (1); asthma (1); autoimmune disease (1); breast carcinoma (1); cardiovascular disease (1); colon (1); colorectal adenocarcinoma (1); dermatitis (1); eosinophilia (1); Familial adenomatous polyposis (1); fibromyalgia (1); infectious disease (1); injury (1); intestinal cancer (1); irritant dermatitis (1); ischemia (1); lung disorder (1); melanoma (1); neurological disease (1); ovarian tumors (1); respiratory disorder (1); sterility (1); viral infection (1).